PF4 (platelet factor 4)
Diseases named in the same sentence as PF4 in open-access papers (continued):
Sharing a sentence is not in itself a finding about the gene and the disease.
myeloma (3 papers, 2011 to 2017). "In this study, we stably transfected human myeloma cell lines with the PF4 gene or the sequence encoding its more potent p17-70 peptide and investigated the effects of PF4 and p17-70 on angiogenesis and tumor growth in vitro and in a SCID-rab myeloma model." (PMID 21693026, 2011). "We found that the attenuated production of VEGF in myeloma cells overexpressing PF4 or p17-70 was associated with the reduced migration of EPCs in vitro." (PMID 21693026, 2011). "We showed that the transfection of the PF4 gene or a sequence encoding p17-70 suppressed the growth of the human myeloma cells in the SCID mice, causing a marked reduction in the tumor volume." (PMID 21693026, 2011). "PF4 or p17-70 also caused a significant reduction in microvessel densities in myeloma xenografts and markedly reduced the tumor volume in the SCID mice." (PMID 21693026, 2011). "We then determined whether the reduced tumor size in the SCID-rab mice inoculated with myeloma cells stably expressing PF4 or p17-70 was associated with a reduction in the production of the human immunoglobulin light chain." (PMID 21693026, 2011). "We also found significantly reduced serum levels of VEGF in the SCID-rab model of myeloma expressing PF4 or the p17-70 fragment." (PMID 21693026, 2011). "Our analysis of MVD in the SCID-rab model of myeloma further showed that myelomas overexpressing PF4 or p17-70 exhibited markedly reduced angiogenesis." (PMID 21693026, 2011). "Similarly, PF4 has been shown to inhibit the migration of human endothelial progenitor cells, as well as to suppress microvessel formation in myeloma xenografts." (PMID 22916307, 2012). "Our genomic analysis of human myeloma cells showed that the PF4 gene is frequently silenced by promoter hypermethylation, which could contribute to the aberrant angiogenesis in MM." (PMID 21693026, 2011). "Our findings indicate that PF4 or p17-70 could be valuable in combating multiple myeloma by disrupting tumor angiogenesis." (PMID 21693026, 2011). "Therefore, we hypothesized that the overexpression of the PF4 gene or p17-70 in MM cells would inhibit the growth of myeloma by inhibiting the functions of proangiogenic factors such as FGF2 and VEGF." (PMID 21693026, 2011). "We also examined the effects of PF4 and p17-70 on the overall survival (OS) of SCID mice bearing human U266 myeloma xenografts." (PMID 21693026, 2011). "Kaplan-Meier analysis demonstrated that PF4 and p17-70 significantly extended the overall survival of SCID mice bearing human myeloma xenografts." (PMID 21693026, 2011). "Kaplan-Meier analysis further demonstrated that PF4 and p17-70 significantly extended the OS of SICD mice bearing human myeloma xenografts." (PMID 21693026, 2011). "We further investigated the effects of PF4 and the p17-70 fragment on cell proliferation, and showed that both of them expressed in U266, RPMI8226, and LP-1 myeloma cells markedly inhibited the proliferation of human EPCs to 67%, 73%, 58%, and 49%, 56%, 42%, respectively (all P < 0.05)." (PMID 21693026, 2011). "Because local blood vessel formation is associated with the growth and metastasis of tumors, we investigated whether PF4 and p17-70 inhibited the production of VEGF in SCID mice bearing human myeloma xenografts." (PMID 21693026, 2011). "We generated stable human myeloma cell lines (U266, RPMI8226, and LP-1) expressing PF4 or p17-70." (PMID 21693026, 2011).
osteoporosis (3 papers, 2021 to 2025). A condition of reduced bone mass, with decreased cortical thickness and a decrease in the number and size of the trabeculae of cancellous bone (but normal chemical composition), resulting in increased fracture incidence. "Integrin α5β1 contributes to osteoporosis pathogenesis via multiple signaling cascades, among which the PF4–α5β1–FAK–ERK axis is particularly critical." (PMID 40894924, 2025). "Given the multiple physiological effects of PF4, we speculated that it may downregulate the proliferation or osteogenic differentiation of BMMSCs, which may be relevant to osteoporosis." (PMID 37565509, 2023). "Therefore, this study aimed to confirm the relationship between PF4 and osteoporosis, evaluate the effects of PF4‐triggered bone destruction in mice in vivo, and determine the mechanism underlying the suppression of osteogenesis or proliferation of BMMSCs induced by PF4." (PMID 37565509, 2023). "The effect of platelet factor 4 (PF4) on bone marrow mesenchymal stem cells (BMMSCs) and osteoporosis is poorly understood." (PMID 37565509, 2023).
tuberculosis (3 papers, 2012 to 2022). A chronic, recurrent infection caused by the bacterium Mycobacterium tuberculosis. "Fibrinogen and FI + II concentrations were higher in patients with HIV-tuberculosis than in controls, and PF-4 concentrations were lower." (PMID 28363198, 2017). "In an in vitro study, platelet activation was evaluated according to the levels of platelet factor-4, and a correlation of good degree was shown between the platelet activation and radiological extent of tuberculosis." (PMID 23114411, 2012).
type 2 diabetes (3 papers, 2015 to 2021). "Moreover, in multivariate analysis PF4 was an independent predictor of both Ks and t50% in type 2 diabetes, which suggests that activated platelets directly contribute to unfavorable fibrin clot phenotype in this disease." (PMID 25928628, 2015).
acute leukemia (2 papers, 2014 to 2023). A clonal (malignant) hematopoietic disorder with an acute onset, affecting the bone marrow and the peripheral blood. "Considering the presence of multiple lineage markers (e.g., DNTT, PF4, and CA1) in the Stem11 genes, Stem11-high AML may capture features reminiscent of acute leukemia of ambiguous lineage, which is associated with immature cells of origin and inferior prognosis." (PMID 38116120, 2023). "Several proteomic studies revealed that PF4 and CTAP-III were decreased in acute leukemia and MDS comparing with HCs." (PMID 25317080, 2014).
adenovirus infection (2 papers, 2022 to 2025). "At the level of patient-derived antibodies, the striking similarity in autoantibody fingerprints between these two conditions strongly indicates that VITT and adenovirus infection-associated anti-PF4 disorders represent a distinct category of adverse immune responses targeting adenoviral structures." (PMID 40733710, 2025). "Another source of PF4 autoantibody production may be natural adenovirus infections, which complicate 5 to 7% of hospitalized SARS-CoV-2 patients and are present in a very high percentage of hepatitis A-infected patients." (PMID 36232795, 2022).
age (2 papers, 2025). A temporal measurement of the time period elapsed since an identifiable point in the life cycle of an organism. "Moreover, systemic administration of PF4 in aged mice reduced hippocampus inflammation and promoted synaptic plasticity, highlighting the potential of PF4 as a pro‐cognitive factor for treating age‐related neurodegenerative diseases." (PMID 39375979, 2025).
allergic asthma (2 papers, 2022). A asthma with a basis in a pathological type I hypersensitivity reaction. "There is ample evidence suggesting that platelet-specific products, including PF4, β-TG, and platelet microparticles, are elevated in allergic asthma subjects, confirming the presence of platelet activation in allergic asthma." (PMID 35432313, 2022). "An increasing body of evidence suggests that in patients with allergic asthma, platelet-specific derived mediators such as platelet factor 4 (PF4) and beta-thromboglobulin (β-TG) increase in the serum, indicating platelet activation." (PMID 35432313, 2022). "In 1981, a study reported that plasma PF4 was increased in patients with allergic asthma, providing the first evidence of the relationship between platelet activation and allergic asthma." (PMID 35432313, 2022).
allergies (2 papers, 2022 to 2025). "Next, PEVs can be positive for Platelet-factor 4 (PF4) and PF4 increases in people with seasonal allergies when they are experiencing symptoms." (PMID 35887184, 2022).
amyotrophic lateral sclerosis (2 papers, 2013 to 2025). Amyotrophic lateral sclerosis (ALS) is a neurodegenerative disease characterized by progressive muscular paralysis reflecting degeneration of motor neurons in the primary motor cortex, corticospinal tracts, brainstem and spinal cord. "PF4 is a specific protein synthesized by platelets, and the neuroprotective effects of PF4 have been demonstrated in mouse models of traumatic brain injury, amyotrophic lateral sclerosis, and Parkinson’s disease." (PMID 40264462, 2025).
ANCA-associated vasculitis (2 papers, 2021 to 2025). "While NETosis functions as a vital host defense mechanism, its dysregulation can result in distinct pathological outcomes such as necroinflammation in ANCA-associated vasculitis (AAV) and thrombosis in anti-PF4 immune disorders." (PMID 40276517, 2025).
chronic kidney disease (2 papers, 2023). Impairment of the renal function secondary to chronic kidney damage persisting for three or more months. "A total of four clinical trials focused on PF4, two of which were medical diagnostic devices and two of which were drugs, in patients with HIT, thrombosis, coronary artery bypass graft surgery presence of heparin/PF4 antibody, and end-stage renal disease." (PMID 36926331, 2023).
chronic lung infection (2 papers, 2021 to 2024). "The Pf4 phage is also associated with increased virulence in a mouse infection model, and it has recently been shown that there is a positive correlation between the presence of Pf phage and chronic lung infection." (PMID 34452479, 2021).
Cirrhosis (2 papers, 2019 to 2021). A chronic disorder of the liver in which liver tissue becomes scarred and is partially replaced by regenerative nodules and fibrotic tissue resulting in loss of liver function. "The results revealed the significant diagnostic values of PF4 and PPBP in cirrhotic HCC, and CCL19, CCL25 in non-cirrhotic HCC, while no significant diagnostic values of CNR1 in HCC with or without cirrhosis were found." (PMID 31346321, 2019).
clear cell ovarian cancer (2 papers, 2018 to 2025). "Similarly, platelet factor 4 (PF4) also known as chemokine (C-X-C Motif) ligand 4 (CXCL4) is highly expressed on macrophages in endometriomas, but not on tumor-associated macrophages of clear cell ovarian cancers." (PMID 30087267, 2018).
CMV infection (2 papers, 2025). "Unique features are the temporal relation to CMV infection, the novel PF4 epitope and the markedly high monoclonal antibody titre (0.2–1 g/L)." (PMID 40298004, 2025). "Further unique features include no proximate adenoviral vaccine or adenovirus exposure, recent cytomegalovirus (CMV) infection and high‐titre anti‐PF4 antibody, detectable as a paraprotein." (PMID 40298004, 2025).
cognitive decline (2 papers, 2023 to 2025). "These behavioural data indicate that systemic PF4 administration enhances cognitive function in aged mice, whereas the loss of PF4 accelerates cognitive decline in an age-dependent manner by middle-age." (PMID 37587343, 2023). "In clinical practice, selecting PF4 as a therapeutic target may delay or rescue cognitive decline in old age by inhibiting the neuroinflammatory response." (PMID 40193115, 2025).
head and neck cancer (2 papers, 2023 to 2024). A primary or metastatic malignant neoplasm affecting the head and neck. "Similarly, in human head and neck cancer tumor cells, Pf4 overexpression reduces tumor growth and increases survival." (PMID 38081853, 2023).
Hypoglycemia (2 papers, 2015 to 2021). A decreased concentration of glucose in the blood. "In our study although there was only a trend towards increased platelet activation in hypoglycemia, a significant correlation inverse correlation between PF4 and Ks was observed." (PMID 25928628, 2015). "At hypoglycemia, however, four proteins changed in controls from baseline [Thrombospondin-1 (p < 0.014), platelet factor-4 (p < 0.01), Platelet basic protein (p < 0.008), and Vitamin K-dependent protein-C (p < 0.00003)], and one protein changed in T2D [Vitamin K-dependent protein-C, (p < 0.0002)]." (PMID 34248840, 2021).
injury (2 papers, 2018 to 2019). Damage inflicted on the body as the direct or indirect result of an external force, with or without disruption of structural continuity. "However, the administration of PF4 concomitantly to GalN/LPS did not further increase this effect, suggesting that the dose-dependent high peak plasma concentration of APC was achieved in the earlier phase of liver injury." (PMID 30971954, 2019).
liver failure (2 papers, 2013 to 2024). A liver disease characterized by the liver losing or has lost all of its function. "In the present study, levels of platelet factor 4 precursor decreased in the progression of hepatitis B to liver failure." (PMID 24223640, 2013).
lupus nephritis (2 papers, 2018 to 2022). Glomerulonephritis in the context of systemic lupus erythematosus. "Urine ALCAM and PF4 appear to have the greatest promise as SLE and lupus nephritis activity indicators, outperforming conventional markers in distinguishing active SLE and LN patients." (PMID 35720325, 2022). "Among active lupus nephritis patients, urine VCAM-1 (r 0.57, P<0.0001), ALCAM (r 0.53, P<0.0001) and PF4 (r 0.50, P<0.0001) exhibited the best correlations with renal SLEDAI." (PMID 35720325, 2022).
Macrothrombocytopenia (2 papers, 2017 to 2023). "Moreover, we have previously shown that mice with MK/platelet-specific RhoA-deficiency (RhoAfl/fl Pf4-cre, further referred to as RhoA−/−) exhibit pronounced macrothrombocytopenia." (PMID 28643773, 2017). "Another study using the conditional knockout Mx-Cre Cdc42fl/fl mice also had macrothrombocytopenia and significantly prolonged bleeding times similar to the Pf4-Cre Cdc42fl/fl mice." (PMID 36768837, 2023). "Experiments using Pf4-Cre Cdc42fl/fl showed that Cdc42 is involved in platelet production since these mice had shortened platelet lifespan and mild macrothrombocytopenia." (PMID 36768837, 2023).
metastatic melanoma (2 papers, 2013 to 2021). A melanoma that has spread from its primary site to another anatomic site. "Similar results were observed in phase I study of recombinant platelet factor 4 in patients with metastatic melanoma and renal cell carcinoma." (PMID 23800319, 2013). "As such, based on studies, the PF4/CXCL4 recombinant protein could be a therapeutic option in combination with CAR T cell therapy for metastatic melanoma by preventing angiogenesis." (PMID 34207884, 2021). "Clinical trials testing recombinant PF-4 have been completed in metastatic colon cancer, AIDS-related Kaposi’s sarcoma, metastatic melanoma, renal cell carcinoma and high-grade glioma." (PMID 23800319, 2013).
metastatic tumors (2 papers, 2013 to 2017). "We thus looked into PF4 mRNA levels from the primary tumor tissues, in some cases metastatic tumors." (PMID 27223426, 2017). "However, it is surprising to see that there was no further benefit in the 4T1 metastatic tumors since the VNTANST targeting should have increased the intratumoral level of PF4, yet thettPF4 did not reduce vessel density in the primary tumors." (PMID 24369443, 2013).
nephritis (2 papers, 2016 to 2022). Inflammation of renal tissue. "Urinary ALCAM, PF4, and VCAM-1 are potential biomarkers for predicting kidney disease activity in cSLE and hold potential as surrogate markers of nephritis flares in these patients." (PMID 35720325, 2022).
oral cancer (2 papers, 2021). "EV packaged platelet factor 4 variant has been identified in plasma from patients with oral cancer previously underscoring the potential importance of this as a biomarker." (PMID 34571828, 2021). "Further comparisons revealed notable elevations of IL-6, IL-8, TNF-α, HCC-1, and PF-4 levels in OSCC collated to OL sample cohorts, with increases traceable from early oral cancer stages." (PMID 33924500, 2021). "The significant increase marked by HCC-1 and PF-4 in OSCC, compared to OL, being detectable from the early onset of this malignancy brings new insights into the identification of prognostic, liquid biopsy-derived candidate biomarkers for oral cancer." (PMID 33924500, 2021).
parasitemia (2 papers, 2022 to 2024). "A total of 10 fresh P. vivax isolates with > 60% mature trophozoites (median of parasitemia 6800 parasites/μL; IQR: 5440–11,348) were used to test whether PLT activation, specifically the release of PF4/CXCL4, takes place in response to direct interaction with Pv-IEs." (PMID 34991449, 2022).
periodontal disease (2 papers, 2023 to 2024). "Of note, recent research has supported the hypothesis that the systemic administration of aspirin induced a significant decrease in the level of PF4 in a rat model of periodontal disease." (PMID 37565509, 2023).
polycystic ovary syndrome (2 papers, 2023 to 2025). A disorder that manifests as multiple cysts on the ovaries. "Moreover, PF4 is also involved in the physiopathological process of chronic obstructive pulmonary disease (COPD), pancreatic cancer, periodontitis, polycystic ovary syndrome (PCOS), and thyroiditis." (PMID 36926331, 2023).
Portal vein thrombosis (2 papers, 2017 to 2021). Thrombosis of the portal vein and/or its tributaries, which include the splenic vein and the superior and inferior mesenteric veins. "Both patients manifested pulmonary and portal vein thrombosis and high level of antibodies to platelet factor 4-polyanion complexes." (PMID 34341358, 2021).
pulmonary TB (2 papers, 2021 to 2022). "While VEGF-A can be considered a potent angiogenic mediator that favors pulmonary TB lesions, PF4 is related to the inflammatory process." (PMID 36325331, 2022). "Elevated plasma concentrations of platelet factor 4 (PF4; CXCL4), a component of alpha granules specific to platelets, are found in patients with pulmonary TB and correlate with radiological disease severity." (PMID 34093524, 2021).
rheumatic disease (2 papers, 2016 to 2022). "However, the prevalence of anti-PF4/heparin Abs has not been investigated in other rheumatic diseases, including RA." (PMID 27558507, 2016).
sarcopenia (2 papers, 2024 to 2025). Progressive decline in muscle mass due to aging which results in decreased functional capacity of muscles. "For example, the EXERNET‐Elder 3.0 project identified PF4 and C1R as potential EV biomarkers for sarcopenia, with strong associations to muscle function and physical performance but not muscle mass." (PMID 40162588, 2025). "PF4 protein has an AUC value of 0.89 [95% confidence interval (CI): 0.82–0.96], so its diagnostic power for sarcopenia would be considered excellent to exceptional." (PMID 39009419, 2024). "Our results support the determination of EV PF4 and C1R as plasma diagnostic biomarkers in sarcopenia and open the door to investigate the role of the content of these vesicles in the pathogeny of the disease." (PMID 39009419, 2024). "Moreover, PF4 and C1R proteins arise as promising diagnostic biomarkers for the identification of sarcopenia in routine clinical practice facilitating prevention and early and more effective interventions." (PMID 39009419, 2024). "Among the candidate proteins, PF4 and C1R showed the largest differences in concentration within sEVs between the sarcopenia and robust individuals." (PMID 39009419, 2024). "Choosing the optimal for PF4, 80% sensitivity and 85.71% specificity was reached while the optimal cut‐off value of C1R would allow sarcopenia diagnosis with 75% sensitivity and 66.67% specificity." (PMID 39009419, 2024). "Moreover, both sarcopenia and robust patient samples were processed following the same protocol; thus, potential technical limitations are not likely to underlie major differences observed in PF4 and C1R levels." (PMID 39009419, 2024).